USP7 (ubiquitin specific peptidase 7)
Diseases named in the same sentence as USP7 in open-access papers (continued):
Sharing a sentence is not in itself a finding about the gene and the disease.
renal fibrosis (1 paper, 2022). A final common manifestation of a wide variety of chronic kidney diseases characterized by glomerulosclerosis and tubulointerstitial fibrosis. "Moreover, our data indicated that the FAT10/USP7/CHK1 axis is positively associated with renal fibrosis in kidneys obtained from patients with calculi-related CKD." (PMID 36152057, 2022). "In this study, we demonstrated that FAT10 accelerates renal fibrosis by stabilizing USP7 to promote CHK1-mediated G2/M arrest in RTECs." (PMID 36152057, 2022). "Additionally, the FAT10/USP7/CHK1 axis was activated in kidneys from patients with calculi-related CKD, thereby leading to renal fibrosis." (PMID 36152057, 2022).
respiratory infection (1 paper, 2025). "The findings suggest that modulating the activity of TRAF1, USP7, and SP1 could provide a novel approach for managing this common and potentially severe respiratory infection in infants." (PMID 40121492, 2025).
rheumatoid arthritis (1 paper, 2024). A chronic, systemic autoimmune disorder characterized by inflammation in the synovial membranes and articular surfaces. "Moreover, in rheumatoid arthritis, USP7 is connected to the migration of synoviocytes that resemble fibroblasts." (PMID 38302916, 2024).
Salmonella Infections (1 paper, 2022). Infections with bacteria of the genus SALMONELLA. "In the present study, we also revealed a critical impact of USP7 on mouse susceptibility to Salmonella infection." (PMID 36032091, 2022).
spinocerebellar ataxia type 1 (1 paper, 2022). Spinocerebellar ataxia type 1 (SCA1) is a subtype of type I autosomal dominant cerebellar ataxia (ADCA type I) characterized by dysarthria, writing difficulties, limb ataxia, and commonly nystagmus and saccadic abnormalities. "USP7 also interacts with ATXN1, which is associated with spinocerebellar ataxia type 1 (SCA1), an autosomal dominant neurodegenerative disorder characterized by several neurological defects and symptoms." (PMID 35159365, 2022).
steatosis (1 paper, 2020). Increased lipid within the cytoplasm of cells. "Similar results were observed, confirming the higher abundance of USP7 and ZNF638 in steatosis-related HCC." (PMID 33040080, 2020).
sterility (1 paper, 2024). "Deletion of one interactor, ubiquitin-specific protease 7 (Usp7), results in impairment of somatic cell differentiation, germ cell nest breakdown, and ovarian development, leading to sterility." (PMID 38517962, 2024).
tauopathies (1 paper, 2025). "In our in vitro tauopathy model using rTg4510 cortical neurons knockdown of Usp7 and Usp10 significantly reduced seeded TAU aggregation without affecting normal human TAU levels." (PMID 41303552, 2025). "Usp7 has been shown to stabilize TAU through deubiquitination, and its silencing in a tauopathy mouse model ameliorated memory deficits, microglial activation, and TAU seeding activity." (PMID 41303552, 2025). "The deubiquitinating enzymes Usp7 and Usp10 strongly influenced seeded TAU aggregation across various in vitro and ex vivo tauopathy models." (PMID 41303552, 2025). "Targeting USP7 and USP10 may offer a novel therapeutic strategy for AD and related tauopathies." (PMID 41303552, 2025).
urothelial bladder cancer (1 paper, 2019). "In this investigation our aim has been to analyse CCDC6 and USP7 expression levels in a series of primary urothelial bladder cancer, arranged in a Tissue Micro Array (TMA), by immunohistochemistry." (PMID 30786932, 2019). "The pharmacological inhibition of the deubiquitinase enzyme USP7 has shown antitumor properties in several tumor types and also determined cytotoxic effects in a series of urothelial bladder cancer cells expressing appreciable levels of CCDC6 and USP7 proteins at western blot." (PMID 30786932, 2019).
UV-sensitive syndrome (1 paper, 2019). UV-sensitive syndrome is a condition that is characterized by sensitivity to the ultraviolet (UV) rays in sunlight. "A mutation in the UVSSA gene has been found to be causative for the autosomal recessive disorder UV-sensitive syndrome in humans and together with USP7 it mediates the transcription-coupled nucleotide excision repair." (PMID 31261764, 2019).
cancer (273 papers, 2010 to 2026). A tumor composed of atypical neoplastic, often pleomorphic cells that invade other tissues. "Conversely, USP7 inhibitors—though promising for cancer—risk inducing HSC exhaustion, as evidenced by our transplantation assays." (PMID 41522346, 2026). "The finding that USP7 interacts with Ezh2 is consistent with previous reports where USP7 was found to interact with and stabilize Ezh2 and that loss of USP7 reduced Ezh2 expression in cancer cells." (PMID 40247205, 2025). "Disruptions, such as overexpression of USP7, have been linked to poor cancer prognosis, highlighting the significance of its regulation in cellular integrity." (PMID 40166258, 2025). "Recent studies showed that USP7 interacts with Ezh2 and promotes its stabilization in cancer cells and that loss of USP7 leads to Ezh2 destabilization." (PMID 40247205, 2025). "USP7 stands out due to its implicated oncogenic properties in cancer, capturing significant interest for its role in the regulation and maintenance of cellular processes, including those associated with epigenetic mechanisms." (PMID 39051184, 2024). "Previous findings in cancer cells have indicated that hypoxia‐induced K63‐polyubiquitinated USP7 deubiquitinates HIF‐1α causing CBP‐mediated H3K56 acetylation on the gene promoter of HIF‐1α to advance epithelial‐to‐mesenchymal transition and metastasis." (PMID 38602256, 2024). "The inhibition of USP7 disrupts the PD‐L1/PD‐1 interaction, increasing the susceptibility of cancer cells to T cell‐mediated killing both in vitro and in vivo." (PMID 39678489, 2024). "Broadly speaking, USP7 expression shows an upward trend in various cancer types and is closely associated with cancer onset, progression, and drug resistance." (PMID 39767641, 2024). "We report a critical role for USP7 in regulation of HIF‐1α mediated VEGF production by cancer‐associated fibroblasts (CAFs) leading to reprograming of the TME." (PMID 38602256, 2024). "Aberrant USP7 expression associated with a variety of human malignancies by regulating the activity of cancer-promoting or cancer-suppressing proteins and often correlates with unfavarable prognosis and metastasis." (PMID 38389844, 2024). "USP7 interacted with PD-L1, enhancing its stability, whereas inhibiting USP7 reduced the PD-L1/PD-1 interaction and made cancer cells more susceptible to T cell-mediated destruction." (PMID 38638430, 2024). "As such, we propose USP7 inhibitors as a new class of small molecule immune modulators specifically targeting cancer‐associated fibroblasts with therapeutic potential in solid tumours that are unresponsive to existing immune oncology treatments." (PMID 38602256, 2024). "USP7 is expressed at high levels in many cancer tissues and is frequently associated with poor prognosis and metastasis." (PMID 37667522, 2023). "Elevated levels of ubiquitin-specific protease 7 (USP7) are associated with poor survival in many cancers." (PMID 36428632, 2022).
cancer (continued). "These USP7/TAZ positively associated genes were significantly enriched in cancer-related epigenetic regulation and protein modifications." (PMID 35931679, 2022). "We report here that the PRC2 complex is physically associated with ubiquitin-specific protease USP7 in cancer cells where USP7 acts to deubiquitinate and stabilize EZH2." (PMID 33849069, 2021). "Ubiquitin-specific peptidase 47 (USP47), a member of the ubiquitin-specific protease family with high homology to USP7, is an active molecule with a wide range of functions and is closely associated with cancer and other diseases." (PMID 34604226, 2021). "Our study emphasizes the need to carefully evaluate dosage-dependent efficacy when considering inhibitors for cancer treatment of USP7 and other genes that are implicated by mutational analysis as haploinsufficient tumor suppressors in some types of cancer." (PMID 33664368, 2021). "Accumulated evidence has shown that abnormal expression and activity of USP7 are associated with a variety of cancers." (PMID 34869041, 2021). "USP7 has been shown to be involved in a variety of biological processes in cells, and is associated with many cancers through the regulation of its downstream substrates." (PMID 34869041, 2021). "Many of the DUBs known to be involved in cancers are also redox-sensitive, such as USP7, which has been implicated in liver cancer and leukemia, and A20, which is involved in metastatic cancers." (PMID 34391779, 2021). "The association of USP7 with cancer has sparked a major interest in the development of USP7 inhibitors as anti-cancer therapies." (PMID 30804394, 2019). "USP7 is also involved in other cancer-associated mechanisms such as DNA damage and repair, epigenetic regulation, human terminal erythoid differentiation and immune responses by regulating other cancer-related targets such as N-Myc, FOXO, PTEN and Claspin." (PMID 31730000, 2019). "The fact that we were not able to obtain complete USP7 KO in APC-mutated CRC cells indicates the essential role of USP7 in cancer cell survival." (PMID 29045831, 2017). "Collectively these data indicates that USP7 depletion causes genomic instability, one of the key hallmarks of cancer." (PMID 25003721, 2014). "Deregulation of USP7 activity has been linked to cancer, making USP7 inhibition an appealing anti-cancer strategy." (PMID 25003721, 2014).
cancer (continued). "USP7 is a member of the USP family that is closely associated with cancer progression." (PMID 40000422, 2025). "The cysteine protease ubiquitin‐specific protease 7 (USP7), also known as herpes‐associated ubiquitin‐specific protease (HAUSP), has gained increasing attention in recent years due to its proven overexpression in several cancer types and its role in tumorigenesis." (PMID 40785232, 2025). "As known that UV stimulation can cause DNA damage in cells and abnormal repair of DNA damage causes tumourigenesis, thus we hypothesized that the USP7‐DICER axis regulating cancer occurrence and development may be involved in DNA damage repair." (PMID 37867415, 2024). "Deubiquitinase ubiquitin-specific protease 7 (USP7), also known as herpesvirus-associated ubiquitin-specific protease (HAUSP), has been regarded as an important regulator of tumorigenesis in several cancers, but its potential roles in ccRCC and the underlying mechanisms have long been mysterious." (PMID 39406703, 2024). "Moreover, the deubiquitinating enzyme USP7 stabilizes hnRNPA1, facilitating the secretion of exosomes derived from cancer-associated fibroblasts that transfer miR-522, thereby enhancing the resistance of GC cells to cisplatin chemotherapy." (PMID 39605891, 2024). "Elevated expression levels of USP7 may suppress ferroptosis, which facilitates cancer cell proliferation, thereby causing an unfavorable prognosis." (PMID 38787520, 2024). "Pathway enrichment analysis using these 535 overlapped genes showed that USP7-associated pathways were involved in several important cellular processes, including cell cycle (G2M and mitotic spindle), cancer metabolism (xenobiotic and fatty acids) and ER stress (unfolded protein response)." (PMID 39406703, 2024). "Additionally, USP7 elimination promotes the polyubiquitination and subsequent degradation of PD-L1, thereby increasing the susceptibility of cancer cells to T-cell-mediated cytotoxicity." (PMID 39605891, 2024). "Moreover, treatment with USP7 inhibitors has been reported to cause the accumulation of polyubiquitinated proteins, leading to ER stress induction in cancer cells." (PMID 37874827, 2023). "In addition, USP7 is involved in the regulation of several key signal transduction proteins associated with cancer development, such as PTEN, FoxO4, HIF-1α, and PHF8." (PMID 38276639, 2023). "Furthermore, SAMHD1 levels positively correlates with USP7 in various human carcinomas, and is associated with an unfavorable survival outcome in patients who underwent chemotherapy." (PMID 37081042, 2023). "Ubiquitin-specific protease 7 (USP7) regulates the stability of a plethora of intracellular proteins involved in the suppression of anti-tumor immune responses and its overexpression is associated with poor survival in many cancers." (PMID 36428632, 2022). "However, in respect of the various functions of USP7 in cell processes, the association between USP7 and cancers, and USP7 targeted cancer therapy, there are still many fields that need to be further explored." (PMID 34869041, 2021). "Paclitaxel and cisplatin promote miR-522 secretion from cancer-associated fibroblasts by activating USP7/hnRNPA1 axis, leading to arachidonate lipoxygenase 15 suppression and decreased lipid-ROS accumulation in cancer cells and ultimately promote acquired chemoresistance in gastric cancer." (PMID 33967786, 2021). "In addition, mutations that influence the status of CDK1 in cancer cells will be determined for the application of USP7 inhibitors in the clinic." (PMID 34445496, 2021).